MYCN (MYCN proto-oncogene, bHLH transcription factor)
Diseases named in the same sentence as MYCN in open-access papers (continued):
Sharing a sentence is not in itself a finding about the gene and the disease.
neuroblastoma (continued). "This confirmed that the small molecule inhibitor vismodegib potentiated the effects of topotecan, via targeting of the hedgehog pathway as an integrated mechanism together with topoisomerase-1 inhibition in the treatment of MYCN amplified, therapy-resistant neuroblastoma." (PMID 26934655, 2016). "We assessed whether ZSTK474 and NVP-BEZ235 could inhibit tumor progression using a transgenic model of neuroblastoma (TH-MYCN), in which tumor formation is driven by tissue-specific overexpression of MYCN within murine neural crest." (PMID 27438153, 2016). "Here, we report that loss of the nf1a orthologue, which is much more highly expressed than nf1b during early PSNS development, greatly accelerates the onset of neuroblastoma induced by MYCN overexpression, with nearly complete penetrance by 5 weeks of age in nf1-deficient zebrafish." (PMID 27130733, 2016). "Therefore, it is likely that MYCN-driven anti-apoptotic signals are particularly critical for tumorigenesis in neuroblastoma in order to counter these pro-apoptotic signals." (PMID 26859456, 2016). "The significance of MYCN amplification in neuroblastomas was first noted in the 1980s." (PMID 26771642, 2016). "Upon ABT-263 treatment, the exogenous MYCN-expressing WT neuroblastoma cells demonstrated a marked increase in cleaved PARP expression compared with the GFP-expressing controls; consistently, these cells had enhanced sensitivity to ABT-263 in 3-day viability assays." (PMID 26859456, 2016). "We hypothesized that overexpression of MYCN gene, which is often amplified in neuroblastoma, could play a role in actinomycin D response." (PMID 26728659, 2016). "Therefore, amplification of MYCN can also involve ALK amplification, and neuroblastoma patients bearing both MYCN amplification and ALK mutations are characterized by an unfavorable aggressive neuroblastoma phenotype." (PMID 27049722, 2016). "We then tested the hypothesis that nuclear EYA1 levels are correlated with MYCN levels in primary neuroblastoma tumor specimens." (PMID 28713571, 2016). "Together, these results indicate that MYCN overexpression does not sufficiently block the differentiation-inducing effect of miR-506-3p and miR-449a, and that the two miRNAs can overcome the MYCN oncogenic pathway and exert strong differentiation-inducing effects in neuroblastoma cells." (PMID 27764804, 2016). "However, 13-197, BI2536 and vismodegib were able to suppress cell growth at IC50 of 7.5-9.1 μM, 8.5-15.5 nM and 61.3-75.8 μM against MYCN-amplified neuroblastoma cells, respectively." (PMID 26934655, 2016). "About 15 % of the neuroblastoma present MYCN amplification, an indicator of bad prognosis." (PMID 26728659, 2016). "Thus, loss of either one or both alleles of nf1a blocked the apoptotic response due to overexpression of MYCN in sympathetic neuroblasts, thus promoting tumor cell survival and leading to the development of neuroblastoma at high penetrance." (PMID 27130733, 2016). "In the transgenic mouse or zebrafish model overexpressing MYCN in sympathoadrenal cells, animals developed tumors in the peripheral sympathetic nervous system, similar to neuroblastoma development in humans, and histological comparisons confirmed the similarity of these tumors to human tumors." (PMID 28035989, 2016).
neuroblastoma (continued). "The International Neuroblastoma Staging Series (INSS) stratifies neuroblastoma by risk level, tumor location and dissemination, and MYCN (V-Myc avian myelocytomatosis viral oncogene neuroblastoma derived homolog) amplification, using data from consortia in the United States, Europe, and Japan." (PMID 28035989, 2016). "Here, we investigate potential therapeutic opportunities for MYCN-amplified neuroblastoma." (PMID 26859456, 2016). "Therefore, we propose that SGO1 is a potential molecular target for the treatment of MYCN-amplified neuroblastoma and tumors bearing YAP/TAZ hyperactivation." (PMID 27539729, 2016). "Additionally, the HIFs have also been shown to interact directly with the MYCN/MAX complex in neuroblastoma, which has a complex effect on cellular phenotype." (PMID 27765905, 2016). "Furthermore, as high nuclear MYCN levels are closely related to advanced stage neuroblastomas, we propose that the correlation between high-level nuclear MYCN and nuclear localization of EYA1 would mainly occur in advanced stage neuroblastomas." (PMID 28713571, 2016). "Since 90% of cancer mortality results from metastatic lesions and over 50% of neuroblastoma patients especially those are older than 1 year of age with MYCN amplification present wide-spread metastasis at diagnosis, it is important to understand the pathogenesis of neuroblastoma metastasis." (PMID 28035989, 2016). "Here we focus on MYCN's role in neuroblastoma, the most common extracranial childhood cancer." (PMID 26673823, 2015). "Interestingly, we noticed glutamine deprivation similarly resulted in TXNIP induction and subsequent decrease in glucose uptake and lactate secretion in MYCN-amplified neuroblastoma cells." (PMID 26528759, 2015). "A neural-lineage promoting role for MYCN is very interesting in the context of the neuroblastoma histologic phenotype, where even poorly differentiated tumors show diffuse reactivity for the neural marker synaptophysin, and truly “undifferentiated” tumors are rare." (PMID 26222553, 2015). "Mapping the upstream regulator networks that drive DE genes in highly MNA cells compared with MYCN single copy cells elucidated several central nodes not previously linked to MNA neuroblastoma (e.g. HRAS, MAPK1, RAF1, NEUROG1 and ER)." (PMID 26673823, 2015). "Compatible with this possibility are the findings that transgenic expression of the human MYCN gene in mouse neural crest cells induces neuroblastoma formation in sympathetic ganglia while overexpression in zebrafish induces tumor formation in the adrenal gland equivalent." (PMID 26222553, 2015). "We then established subcutaneous xenografts using Kelly cells to confirm whether GLS2-mediated glutamine catabolism could affect the tumorigenic capacity of MYCN-amplified neuroblastoma cells in vivo." (PMID 26528759, 2015). "We therefore asked whether MYCN-amplified cells are more sensitive to methotrexate than those without MYCN amplification by generating dose-response data for a panel of 13 neuroblastoma cell lines, 7 of which were MYCN-amplified and 6 single copy." (PMID 25860940, 2015). "Small‐molecule inhibitors of PRMT5 may therefore represent a novel therapeutic strategy for neuroblastoma and other cancers driven by the MYCN oncogene." (PMID 25475372, 2015). "However, we previously provided evidence to suggest that integrin α4 plays a role in promoting malignant behaviours in MYCN-amplified neuroblastoma cells." (PMID 25973900, 2015). "This indicates that blocking chromatin modifiers could be of clinical value in MYCN-overexpressing tumors such as neuroblastoma." (PMID 25477524, 2015).
neuroblastoma (continued). "A subsequent study confirmed that higher levels of TAM-specific genes (CD14, CD16, IL6, IL6R and TGFB1) were associated with a worse prognosis in MYCN-nonamplified neuroblastomas." (PMID 26729169, 2015). "Similar results were obtained in primary MYCN-amplified neuroblastoma cells." (PMID 25749379, 2015). "In addition to neuroblastoma and WT, MYCN gain or amplification is now emerging as a common aberration associated with adverse outcome in multiple paediatric malignancies, including rhabdomyosarcoma and medulloblastoma." (PMID 25749049, 2015). "However, our results demonstrate the specific anti-oncogenic potential of β-estradiol in MYCN amplified neuroblastoma, where it reduces cell viability and partially removes the MYCN mediated differentiation block." (PMID 26673823, 2015). "Notably, kinase-independent roles, such as the protein–protein interaction between AurA and MYCN protein that stabilizes MYCN in neuroblastoma, provide a link between regulation of AurA levels and proliferation." (PMID 26835416, 2015). "Here, we show that MYCN interacts with the MAPK pathway at numerous levels, including through protein-protein interactions with component proteins of the pathway, revealing that MAPK can play a role in neuroblastoma even before MAPK mutations occur." (PMID 26673823, 2015). "We previously demonstrated that cultured neuroblastoma cell lines quite commonly express integrin α4, which can contribute to signaling via non-receptor tyrosine kinases following ligation of fibronectin in MYCN-amplified tumor cell lines, such as NB8." (PMID 25973900, 2015). "Interestingly, GLS2 knockdown significantly decreased both GSH content and GSH/GSSG ratio, suggesting that enhanced glutamine deamidation by GLS2 plays an important role in proper redox homeostasis maintenance in MYCN-amplified neuroblastoma cells." (PMID 26528759, 2015). "Notably, we also identified AURKA, a kinase critically required to stabilize the MYCN protein and whose inactivation triggers synthetic lethality in MYCN-amplified neuroblastomas." (PMID 25477524, 2015). "Furthermore, we provide evidence that these miRNAs are preferentially downregulated during MYCN-driven neuroblastoma tumor formation, suggesting that MYCN negatively controls the expression of these miRNAs, and as such safeguards its own expression." (PMID 25294817, 2015). "Therefore, binding partners other than MAX are likely more relevant to driving MYCN-mediated poor neuroblastoma outcome." (PMID 26673823, 2015). "MYCN overexpression in these cells markedly shifted their differentiation toward the neural lineage, compatible with the neural histologic phenotype observed in neuroblastoma." (PMID 26222553, 2015). "In this present study we explored the functional interaction between LSD1 and MYCN and how such an interaction may be critical for Neuroblastoma biology." (PMID 26062444, 2015). "Interestingly, 5 MYCN-targeting miRNAs were positively correlated to MYCN expression or activity, suggesting that MYCN induces their expression in neuroblastoma." (PMID 25294817, 2015). "However, we observed that SapC-DOPS induced mitochondrial Smac and Cyto c release pattern was similar in the two neuroblastoma cell lines examined, despite different MYCN status." (PMID 25889084, 2015). "In this study we explored the functional interaction between LSD1 and MYCN and how such an interaction may be critical for Neuroblastoma biology." (PMID 26062444, 2015). "On one hand the combination of LSD1 and MYCN inhibitors may have strong therapeutic relevance in the context of MYCN-driven Neuroblastoma." (PMID 26062444, 2015). "By broadening in vivo and cell line studies across this new pharmacologic scaffold, these studies add to the growing evidence implicating PI3K/mTOR inhibition as a viable strategy in MYCN-driven pediatric cancers including both neuroblastoma and medulloblastoma." (PMID 26029667, 2015).
neuroblastoma (continued). "The proliferation, apoptosis, and neural lineage commitment induced by MYCN are tumor-like characteristics and thereby support the hypothesis that multipotent adrenal medullary progenitor cells are cells of origin for neuroblastoma." (PMID 26222553, 2015). "Taken together, these results demonstrate an important role of GLS2 in oxidative glutamine metabolism driven by oncogenic N-Myc, suggesting targeting GLS2 may represent an effective treatment approach to neuroblastoma patients exhibiting MYCN-amplification." (PMID 26528759, 2015). "Interestingly, MYCN overexpression or amplification conferred sensitivity to β-estradiol treatment, resulting in reduced neuroblastoma cell viability, although the extent of β-estradiol ITR inhibition did not correlate solely with amplified MYCN expression." (PMID 26673823, 2015). "Therapeutic approaches to tackle high-risk MYCN-amplified neuroblastoma are lacking, and a disproportionate number of high-risk individuals die or suffer treatment related morbidity." (PMID 26673823, 2015). "MYCN status alone is sufficient to predict poor outcome in 20–25% of primary neuroblastoma." (PMID 25973900, 2015). "As due to the heterogeneous nature of the amplification process, no single representative MNA model exists, we also used a panel of neuroblastoma cell lines which broadly represent the range of neuroblastoma, from MYCN single copy to amplified, and which cover a wide range of MYCN expression." (PMID 26673823, 2015). "Whether TXNIP virtually functions downstream of GLS2 to restrict aerobic glycolysis needs further investigation, though we observed prominent induction of this protein in MYCN-amplified neuroblastoma cells upon glutamine starvation and GLS2 knockdown." (PMID 26528759, 2015). "In a previous in vitro study, we found that the glycolytic inhibitor 2-deoxyglucose (2DG) could suppress the growth of neuroblastoma cells, particularly in those with MYCN amplification." (PMID 26398947, 2015). "However, in another study in our laboratory a subset of MYCNsc neuroblastomas were found to have high MYCN protein expression." (PMID 25267348, 2015). "The chemical ITRs showing inhibition in MNA cells versus MYCN single copy cells present candidate therapeutics for MNA neuroblastoma, as treating MNA cells with these drugs could conceivably compromise the detrimental effects of MYCN." (PMID 26673823, 2015). "Growing evidence suggests that MYCN predominantly acts repressively on the overall miRNA composition and we indeed observed widespread downregulation of miRNA expression during murine MYCN-driven neuroblastoma development (gray line)." (PMID 25294817, 2015). "The MYCN model systems, however, cannot confirm the positive correlation between miR-34c-5p and miR-449a and MYCN expression or activity observed in primary neuroblastoma tumors: miR-34c-5p is consistently downregulated in the murine models, whereas the expression of miR-449a is not altered." (PMID 25294817, 2015). "Specifically, loss of 1p36, a region frequently deleted in human MYCN-amplified neuroblastomas, was not recapitulated in our model." (PMID 25174395, 2015). "Conversely, prognostic insights and molecular drivers of the MYCN non-amplified high-risk neuroblastoma, that comprises about 60-70 % of stage 3 and stage 4 disease remains unexplored." (PMID 26148557, 2015). "More importantly, in contrast with its tumor suppressive roles in hepatocellular carcinomas, we showed that GLS2 paradoxically coordinates both glutamine-dependent anapleurosis and aerobic glycolysis to sustain cell proliferation and survival of MYCN-amplified neuroblastomas." (PMID 26528759, 2015).
neuroblastoma (continued). "It represents the most common cancer in children younger than 1 year and is a heterogeneous disease that may either have a very good prognosis (e.g., stage 4S neuroblastoma) or a dismal outlook (e.g., MYCN-amplified neuroblastoma)." (PMID 26225123, 2015). "Notably, three of these excluded miRNAs, let-7e-5p, miR-101-3p and miR-202-3p, have been reported to target MYCN in a MYCN amplified neuroblastoma cell line." (PMID 25294817, 2015). "The intriguing results of this study require substantial biological research, e.g. association with gene expression and molecular data, and in vitro and in vivo MYCN manipulation studies, to elucidate the functional role for MYCN in the metastatic spread of neuroblastoma cells." (PMID 25267348, 2015). "Using the TH-MYCN neuroblastoma mouse model in which human MYCN is expressed under control of the mouse tyrosine hydroxylase promoter, we are able to generate mouse neuroblastoma tumors with high penetrance, which are genetically, histologically, and morphologically similar to human neuroblastomas." (PMID 26029667, 2015). "The majority of the MYCN-targeting miRNAs in neuroblastoma (10 out of 12) showed a significantly decreased expression during tumor development in TH-MYCN+/+ mice compared to normal development, while 2 of them showed no significantly different expression pattern." (PMID 25294817, 2015). "Interestingly, two of the differentially expressed miRNAs (miR-513a-5p and miR-628-3p) have been recently reported dysregulated in human neuroblastomas, in which aberrant expression of MYCN is quite common." (PMID 26453442, 2015). "However, the realm of MYCN amplification is restricted to about 20 % of all cases of neuroblastoma, ~30-40 % of stage 3 and stage 4 and only ~10 % of stage 4 s patients." (PMID 26148557, 2015). "β-Catenin expression in tumour sections was increased in high-risk neuroblastoma without MYCN amplification compared to expression in low- or medium-risk sections." (PMID 25266063, 2015). "A recent study found MYCN gene expression to be required for neuroblastoma cell line differentiation, with an increase in MYCN expression during early phases of retinoic acid-induced differentiation and a strong reduction of neurite formation with MYCN silencing." (PMID 26222553, 2015). "MYC and MYCN activated miR-9, binding directly to the mir-9 locus in neuroblastoma cells." (PMID 26694467, 2015). "Therefore, we provide evidence that MYCN-targeting miRNAs are preferentially downregulated in MYCN-driven neuroblastoma, suggesting that MYCN negatively controls the expression of these miRNAs, to safeguard its expression." (PMID 25294817, 2015). "ERK pathway activation has been previously observed in NF1 mutated neuroblastoma, but not previously found correlated with MYCN expression levels." (PMID 26673823, 2015). "A strong link to a neural crest-derived cell of origin for neuroblastoma was established when mice overexpressing MYCN in neural crest cells under the tyrosine hydroxylase promoter were shown to develop neuroblastoma-like tumors, specifically in the paraspinal sympathetic ganglia." (PMID 26222553, 2015). "LIN28 and KLF4 expression is also elevated by MYCN in neuroblastomas." (PMID 26023799, 2015). "Similarly to MYBL2, MYB expression is significantly increased in MYCN-amplified neuroblastomas predicting poor survival." (PMID 25477524, 2015). "Perhaps ALK-induced upregulation of TRKB, a protein shown to enhance the survival of neuroblastoma-derived cells, may act as a pro-survival factor in the context of MYCN-driven tumor development." (PMID 26222553, 2015). "Here, we present a novel conditional MYCN-driven mouse model that resembles human neuroblastoma." (PMID 25174395, 2015).